XRCC1 (X-ray repair cross complementing 1)
Diseases named in the same sentence as XRCC1 in open-access papers (continued):
Sharing a sentence is not in itself a finding about the gene and the disease.
lung cancer (continued). "The Arg399Gln polymorphism in the XRCC1 gene is associated with the incidence of lung cancer in North Indians." (PMID 40650316, 2025). "ERCC1 and XRCC1 polymorphisms have also been significantly associated with the risk of lung cancer, especially in non-smokers 2-5." (PMID 35069899, 2022). "In addition, overexpressed of XRCC1 and CYP1A1 reversed the inhibitory effect of miR-486-3p mimic on lung cancer cells, which further confirmed the targeted relationship among miR-486-3p and XRCC1 and CYP1A1." (PMID 33500536, 2022). "Furthermore, miR-486-3p mimic reversed the effect of circFLNA overexpression on promoting lung cancer cells and tumors and regulating the expressions of miR-486-3p, XRCC1, CYP1A1, and metastasis/apoptosis/proliferation-related factors." (PMID 33500536, 2022). "Furthermore, Epac has been shown to mediate cAMP-induced inhibition of DNA damage repair in lung cancer by promoting the degradation of X-ray repair cross-complementing protein 1 (XRCC1)." (PMID 32899451, 2020). "Therefore, the effect of Epac-mediated inhibition of XRCC1 should be further investigated to confirm the role of Epac in lung cancer." (PMID 32899451, 2020). "In this report, we found that XRCC1 was stabilized to promote chemoresistance in lung cancer." (PMID 31043584, 2019). "Notably, conditioned medium from two different lung-derived fibroblast lines with XRCC1 KD, significantly stimulated the growth of non-small cell lung carcinoma-derived H1299 cells and lung carcinoma-derived A549 cell lines." (PMID 29568385, 2018). "The study examines the gene-gene interactions between two DNA base excision repair genes on lung cancer risk: the ADPRT (adenosine diphosphate ribosyltransferase) Val762Ala polymorphism and the XRCC1 (X-ray repair cross-complementing group 1) Arg366Gln polymorphism (both having three genotypes)." (PMID 28431517, 2017). "As reports showed that XRCC1 was associated with lung cancer risk, we considered that violation of HWE was not necessarily be excluded in this analysis, and furthermore, no genotyping error was detected in those studies." (PMID 28743242, 2017). "We observed that the Arg194Trp and Arg399Gln genetic polymorphisms in XRCC1 gene were not statistically influenced the median PFS in all advanced lung cancer patients with platinum-based chemotherapy treatment." (PMID 26585370, 2015). "It seemed that the Arg194Trp may be a reliable predictive locus to assess the pharmacogenetics of XRCC1 gene on clinical outcomes of advanced lung cancer patients treated with platinum-based chemotherapy compared with the Arg399Gln based on ORR outcomes." (PMID 26585370, 2015). "However, a study with a larger sample size is needed to further evaluate gene-environment interaction on XRCC1 Arg399Gln, Arg194Trp, Arg280His, −77T>C, and XRCC3 T241M polymorphisms and lung cancer risk." (PMID 23990873, 2013). "In this study, we sought to investigate the association of three well-characterized nonsynonymous polymorphisms in XRCC1 (rs1799782∶Arg194Trp and rs25487∶Arg399Gln) and XRCC3 (rs861539∶Thr241Met) genes with risk of lung cancer in a northeastern Chinese population." (PMID 23409158, 2013). "Results of meta-analysis for XRCC1 and XRCC3 polymorphisms and lung cancer risk." (PMID 23990873, 2013). "Many studies have reported the association of X-ray repair cross-complementing group 1 (XRCC1) Arg399Gln, Arg194Trp, Arg280His, −77T>C, and X-ray repair cross-complementing group 3 (XRCC3) T241M polymorphisms with lung cancer risk, but the results remained controversial." (PMID 23990873, 2013). "In the stratified analyses, there was not still significant association between XRCC1 Arg280His polymorphism and lung cancer risk." (PMID 23990873, 2013). "In this study, we assessed the OGG1 Ser326Cys, MUTYH Gln324His, APEX1 Asp148Glu, XRCC1 Arg399Gln, and XRCC3 Thr241Met gene polymorphisms that may influence DNA repair capacity and their association with the overall survival of lung cancer patients." (PMID 23443124, 2012).
lung cancer (continued). "XRCC1 encodes a protein that complexes with DNA ligase to repair DNA gaps resulting from BER, and a polymorphism at codon 399 Arg to Gln of XRCC1 is associated with the risk of lung cancer." (PMID 23443124, 2012). "Since the study on the association between XRCC1 Arg194Trp polymorphism with PFS or OS was too few to be applied in the present meta-analysis, we only analyzed the association of XRCC1 Arg194Trp polymorphism and objective response in lung cancer patients." (PMID 22339849, 2012). "Both G/A and A/A genotypes of XRCC1 Arg399Gln could influence overall survival of lung cancer patients (G/A vs. G/G: HR, 1.23; 95%CI, 1.06-1.44; A/A vs. G/G: HR, 2.03; 95%CI, 1.20-3.45)." (PMID 22339849, 2012). "We are delighted to find the statistically significant association between XRCC1 SNPs with objective response and overall survival of lung cancer, which were not significant in previous original reports." (PMID 22339849, 2012). "X-ray repair cross-complementing group 1 (XRCC1) protein plays a central role in base excision repair (BER) pathway by interacting with other DNA repair proteins, giving the possibility that XRCC1 has some relationship with the response to therapy and the overall survival of lung cancer." (PMID 22339849, 2012). "In our previous study, a significant association between XRCC1 399Gln/Gln genotype and risk of lung cancer in Chinese non-smoking women was found." (PMID 20003463, 2009). "In agreement with this, a higher risk of lung cancer has been reported for the carriers of the XRCC1 Gln/Gln genotype, although negative studies also exist." (PMID 16280050, 2005). "Therefore, genotyping data from XRCC1 and XRCC3 genes, incorporating the haplotype and synergism analytical strategies would facilitate the identification of individuals at high risk of developing lung cancer in future clinical screening." (PMID 23409158, 2013). "Therefore, functional SNPs in XRCC1 gene may relate with platinum sensitivity and have prognostic values among lung cancer patients." (PMID 22339849, 2012). "Here, we further demonstrated that overexpressions of XRCC1 and CYP1A1 enhanced the viability, proliferation, migration, and invasion of lung cancer cells through regulating related genes." (PMID 33500536, 2022). "SIRT1 is upregulated in chemoresistant lung cancer cells, genetic knockdown or chemical inhibition of SIRT1 reversed chemoresistance by enhancing DNA damage and apoptosis activation, accompanied with XRCC1 degradation." (PMID 31043584, 2019). "The principal finding was XRCC1 gene Arg399Gln and XRCC3 gene Thr241Met per se were significant contributors to lung cancer." (PMID 23409158, 2013). "For practical reasons, we hope that this study will establish background data for further investigations into the mechanisms of XRCC1 and XRCC3 genes and the development of lung cancer." (PMID 23409158, 2013). "We focused on OGG1 Ser326Cys, MUTYH Gln324His, APEX1 Asp148Glu, XRCC1 Arg399Gln, and XRCC3 Thr241Met and examined the relationship between the different genotypes and survival of Japanese lung cancer patients." (PMID 23443124, 2012). "Finally, in order to test whether individual polymorphisms in DNA repair genes might interact and modify the risk of developing lung cancer, ORs were estimated for each pair of the studied polymorphisms (XPC PAT, XPD Asp312Asn, XPD Lys751Gln, XRCC1 Arg399Gln and XRCC3 Thr241Met)." (PMID 17705814, 2007). "Remarkably, inhibition of SIRT7 also enhanced the repression of ARF target genes in ARF-positive Calu-3 lung cancer cells further supporting the hypothesis that SIRT7 controls expression of Nectin2, XRCC1, and SUPT5H in an ARF-dependent manner." (PMID 38870055, 2024). "The data revealed that XRCC1 and CYP1A1 were the targets of miR-486-3p in lung cancer cells." (PMID 33500536, 2022). "Moreover, XRCC1 interacts with ALDH2 and predicts poor OS in patients with lung cancer and liver cancer." (PMID 32258128, 2020).
lung cancer (continued). "We thus conclude that XRCC1 mRNA levels along with ALDH2 mRNA levels may be used for stratification in order to predict the 5-year overall survival rate in liver and lung cancer patients and to refine their treatment strategy." (PMID 30088263, 2018). "Present meta-analysis results were not consistent with a previous meta-analysis on XRCC1 and XRCC3 polymorphisms with lung cancer risk." (PMID 23990873, 2013). "We have determined the frequency of 5 polymorphisms in 4 different genes implicated in DNA damage repair (XPC PAT, XPD Asp312Asn, XPD Lys751Gln, XRCC1 Arg399Gln, and XRCC3 Thr241Met) in lung cancer patients and matched controls in order to evaluate their association with the risk of lung cancer." (PMID 17705814, 2007). "Some genes such as MMP11 (extra-cellular matrix proteins), XRCC1 (DNA repair), VEGF (regulator of angiogenesis), Cyclin D1 (cell cycle regulators) and tumor-suppressor genes (Semaphorin 3B, WNT-5A) have been found as down-regulated genes during lung cancer progression." (PMID 29593668, 2018). "Therefore, genetic polymorphisms of CYP1A1-rs1048943, GSTM1, GSTT1, mEH-rs1051740 and XRCC1(rs1799782, rs25489), methylation of p16 and RASSF1A gene, and telomere length were analyzed in peripheral blood both from lung cancer patients and health controls to explore their correlation." (PMID 29212267, 2017). "The protein expression of hMLH1, hMSH2, XRCC1, XRCC3, XRCC5, BRCA1, and BRCA2 repair genes in B[a]P-treated HPV-positive and -negative lung cancer cells was analyzed by western blotting." (PMID 26918347, 2016).
gastric cancer (34 papers, 2012 to 2025). A primary or metastatic malignant neoplasm involving the stomach. "A large number of studies have reported that XRCC1 is associated with the development, progression, and prognosis of a variety of cancers, such as thyroid cancer, gastric cancer, non-small cell lung cancer, and cervical cancer." (PMID 38217545, 2024). "Further, increased survival after platinum-based chemotherapy regimens in breast, colorectal, non-small-cell lung, esophageal and gastric cancers carrying the XRCC1 rs25487 allele have been observed." (PMID 36497451, 2022). "Molecular studies demonstrate the association between SNPs in XRCC1, the risk of different cancers (gastric cancer, for example) and their predictive value for treatment outcome." (PMID 32821392, 2020). "That is, the XRCC1 genotype modifies the impact of high dietary salt and vegetable oils on the risk of stomach cancer." (PMID 29020930, 2017). "The effect of the XRCC1 gene homozygosity, particularly Arg/Arg, on the risk for stomach cancer was elevated by a high intake of vegetable oils and salt." (PMID 29020930, 2017). "The analysis revealed that the XRCC1 Gln399Arg genotype is a significant effect modifier of environmental risk of stomach cancer for both high vegetable oil consumption (p = 0.036) and high salt intake (p = 0.014)." (PMID 29020930, 2017). "In summary, this study shows a significant effect of high fat and salt intake and the XRCC1 gene as risk factors for stomach cancer." (PMID 29020930, 2017). "In conclusion, the effect of the XRCC1 gene homozygosity, particularly Arg/Arg, on the risk for stomach cancer was elevated by a high intake of vegetable oils and salt." (PMID 29020930, 2017). "This study found that there was an interaction effect between Arg/Arg homozygosity and high salt or vegetable oil intake leading to increased susceptibility to stomach cancer compared to other XRCC1 genotypes." (PMID 29020930, 2017). "Our objective was to investigate effect of environmental risk factors and the XRCC1 gene and how they related to the incidence of stomach cancer." (PMID 29020930, 2017). "Future studies involving other populations need to be conducted to determine if certain XRCC1 genotypes along with vegetable oil and salt intake pose a risk of stomach cancer in those populations." (PMID 29020930, 2017). "The Arg/Arg homozygote polymorphism of the XRCC1 gene was associated with an increased risk of stomach cancer in the Thai population (OR adj, 3.7; 95%CI, 1.30–10.72) compared with Gln/Gln homozygosity." (PMID 29020930, 2017). "The PARP1 rs1136410 synergistically interacted (ORinteraction = 1.84) with XRCC1 rs25487 encoding p.Arg399Gln in gastric cancer risk." (PMID 27588484, 2016). "This meta-analysis aimed to summarize published data about the association between two SNPs of XRCC1 (Arg194Trp and Arg399Gln) and treatment outcomes of patients with advanced gastric cancer." (PMID 24465544, 2014). "Some researchers have studied the association between SNPs in XRCC1 gene and clinical outcome of gastric cancer patients." (PMID 24465544, 2014). "Because the study on the association between XRCC1Arg194Trp polymorphism with PFS or OS was too few to be analyzed, we only analyzed the association of XRCC1 Arg194Trp polymorphism with tumor response in gastric cancer patients in this meta-analysis." (PMID 24465544, 2014). "In addition, chemotherapy's effect and toxicity were greater in patients with XRCC1 mutated non-small cell lung and gastric cancers than in those with high XRCC1 expression." (PMID 38217545, 2024). "Low levels of XRCC1 expression have generally been associated with increased tumour aggressiveness and poorer outcome in triple negative breast cancer, reduced survival in gastric cancer and unresponsiveness to radiotherapy in bladder cancer." (PMID 29568385, 2018). "More recent work suggests that the XRCC1 gene is an important risk factor for stomach cancer." (PMID 29020930, 2017).
gastric cancer (continued). "The aim of this study was to investigate whether the risk of stomach cancer from XRCC1 gene polymorphisms was modified by environmental factors in the Thai population." (PMID 29020930, 2017). "However, the minor variant A allele of XRCC1 399 polymorphism was negatively associated with progression-free survival and 2-year survival in gastric cancer patients." (PMID 24465544, 2014). "However, other cancer such as gastric cancer, colorectal cancer and so on with XRCC1 −77T>C polymorphism remained unclear." (PMID 23990873, 2013). "The XRCC1 Arg194Trp variation has been demonstrated to increase risk of lung and gastric cancer." (PMID 23226774, 2012). "Gastric cancer tissues exhibit substantially higher levels of XRCC1 gene promoter methylation compared to adjacent normal tissues, with the hypermethylation status of this gene promoter significantly associated with protein expression loss." (PMID 38217545, 2024). "More importantly, JWA alone and in combination with XRCC1 or in combination with FAK can also be used as a prognostic marker for the outcome of chemotherapy in patients with resectable gastric cancer." (PMID 36230577, 2022). "In one study, comprising 612 gastric cancer patients, immunohistochemistry (IHC) was used to evaluate XRCC1 protein expression profiles on surgical specimens." (PMID 32821392, 2020). "Detecting XRCC1 expression in people with gastric cancer can provide a clinical guidance when choosing the optimal adjuvant therapy." (PMID 32821392, 2020). "Recently, several studies have investigated the clinicopathological and prognostic significance of XRCC1 in human cancers including gastric cancer, ovarian cancer, and non-small cell lung cancer." (PMID 32426369, 2020). "On the contrary, several reports showed that XRCC1 was down-regulated in glioma, bladder cancer, pancreatic cancer, and gastric cancer." (PMID 32426369, 2020). "In the present study, polymorphic variants of two DNA repair genes, XRCC1 Arg399Gln and XPD Lys751Gln, were chosen to be studied in association with gastric cancer susceptibility in the Kashmiri population." (PMID 30225185, 2018). "A number of evidences have documented the existence of an association of XRCC1 and XPD with an increased risk of gastric cancer." (PMID 30225185, 2018). "In the present study, we detected the polymorphisms of XRCC1 and XPD genes in 180 gastric cancer cases and 200 matched healthy controls." (PMID 30225185, 2018). "For instance, a study conducted in Poland found that XRCC1, XPD and MGMT polymorphisms modified the magnitude of risk associated with low intake of fruits or vegetables and smoking for gastric cancer." (PMID 29020930, 2017). "Previous observation indicated that the expression level of XRCC1 was markedly increased in cisplatin-resistant gastric cancer cells and contributed to cisplatin resistance." (PMID 29117108, 2017). "More interestingly, several association studies also found that SNPs located in DNA repair related genes including ERCC4, ERCC6, Ku70m, APE1, XRCC1, and XPD exhibited a differential effect between genders on gastric cancer susceptibility." (PMID 26402912, 2015). "In previous clinical studies, we confirmed that the expressions of JWA and XRCC1 protein were significant prognostic and predictive biomarker in hepatocellular carcinoma and gastric cancer." (PMID 25925371, 2015). "We performed a systemic review and meta-analysis to assess the evidence about effects of XRCC1 SNPs on the efficacy of chemotherapy and overall survival in gastric cancer patients treated with platinum-based chemotherapy." (PMID 24465544, 2014). "In conclusion, we report for the first time that JWA regulated cisplatin-induced DNA damage and apoptosis through the CK2—P-XRCC1—XRCC1 pathway, indicating a putative drug target for reversing cisplatin resistance in gastric cancer." (PMID 25476899, 2014).